RET (ret proto-oncogene)
Diseases named in the same sentence as RET in open-access papers (continued):
Sharing a sentence is not in itself a finding about the gene and the disease.
tumor (continued). "The consensus also recommends that if the primary tumor harbors a RAS mutation, RET-mutation testing is not necessary, at least at initial diagnosis, since these mutations are mutually exclusive." (PMID 40540622, 2025). "Patient characteristics of the RET and NTRK fusion in CRC and other tumor types." (PMID 39950716, 2025). "Likewise, the rapid evolution of HER2-directed therapies—including bispecific antibodies and antibodies–drug conjugates—and the tumor-agnostic approval of NTRK and RET inhibitors, mark an additional step toward a genomically driven therapeutic paradigm." (PMID 41465387, 2025). "We employed our original approach to assess RET coverage asymmetry in our experimental RNA-seq dataset, which included 1248 whole-transcriptome sequencing (WTS) profiles obtained for samples representing different tumor types." (PMID 41373459, 2025). "Activating RET alterations have been shown to enhance the activity of the PI3K/AKT and MAPK pathways, thereby promoting the proliferation and development of various types of tumor cells." (PMID 38957390, 2024). "Lenvatinib prevents tumor angiogenesis through inhibition of VEGFR-1, -2, and -3, and also blocks the proliferation of tumor cells through inhibition of FGFR-1, FGFR-2, FGFR-3, & FGFR-4, PDGFRα, RET, and c-KIT." (PMID 38622735, 2024). "Out of the 760 samples for which the RET-FISH analysis yielded an interpretable result, 32 (4%) were positive by FISH (≥15% of tumor cells with separated 5′ and 3′ signals or isolated 3′ signals or both) and 728 / 760 (96%) were negative (<15% positive tumor cells)." (PMID 39507413, 2024). "However, L can act on FGR1–FGR4, PDGFR-b, RET, and c-kit, although its main effect is considered to be on VEGFR-1, VEGFR-2, and VEGFR-3 and, hence, on tumor vascularization." (PMID 39045273, 2024). "To date, there have been no other reported cases of LCH or other MAPK pathway-driven neoplasms arising in patients undergoing prolonged RET inhibition." (PMID 38804700, 2024). "Occasional instances of RET rearrangements have been described in breast carcinomas, KRAS mutation-negative pancreatic cancers, and some other tumor types." (PMID 38612902, 2024). "This inhibitory effect is not solely due to decreased tumor burden but interrupts a physiological regulatory role of RET on calcitonin gene expression." (PMID 39030177, 2024). "We found that Pediatric PTCs in the BRAF V600E/RAS/RET negative group (simultaneous negative) tend to have a single lesion with irregular morphology but clear tumor margins." (PMID 38904052, 2024). "RET/PTC1 rearrangement has been confirmed in many PTC cases and thought to be a tumor driver gene." (PMID 39135916, 2024). "New RET-inhibitor, immunotherapy, radioimmunotherapy, MTC tumor–derived vaccines and drugs interfering with the methylation of DNA could represent the most interesting options for the future." (PMID 37979019, 2023). "It functions by inhibiting the growth of tumor cells and the formation of blood vessels through targeting various serine/threonine and tyrosine kinases such as RAF1, BRAF, VEGFR 1, 2, 3, PDGFR, KIT, FLT3, FGFR1, and RET." (PMID 37299411, 2023). "If tumour tissue is inadequate for this testing, another biopsy to obtain additional tumour tissue should be initiated, and if still inadequate, liquid biopsy with NGS (including RET) is recommended." (PMID 37207147, 2023). "High expression of RET in healthy and non-tumorous (histologically normal) tissues is indicative of lack of inactivation of the gene and thus, the absence of tumours." (PMID 36890818, 2023). "Regorafenib is an oral inhibitor of several kinases involved in tumor angiogenesis (VEGFR1-3 and TIE2), oncogenesis (KIT, RET, RAF1, and BRAF), and in the interaction between tumor and microenvironment (PDGFR, FGFR), and tumor immunity (colony-stimulating factor 1 receptor [CSF1R])." (PMID 37071295, 2023).
tumor (continued). "RET fusions lead to the activation of downstream signaling pathways such as STAT3 and RAS-MAPK involved in cell proliferation and survival, thus promoting tumor growth." (PMID 38132167, 2023). "The clinical relevance of these findings was verified through the detection of increases in both RET expression and GDNF-regulated transcriptional pathways in recurrent tumor samples (73.1%) compared to 55.8% of primary tumors, which was reproduced in analysis of the TCGA and NIH ROCK databases." (PMID 36918928, 2023). "These are not exclusive to MTC, as in other RET-altered neoplasia there is already greater experience with promising outcomes." (PMID 37511745, 2023). "Basket trials now enroll patients based primarily on the presence of oncogenic drivers, such as RET (rearranged during transfection) alterations, regardless of tumor type." (PMID 37627175, 2023). "Overall, 42% (48/115) of participants had tumours with high-RET expression, compared to 58% (67/115) without; 44% of participants in the vandetanib group had tumours with high-RET expression compared to 40% in the placebo group." (PMID 39516358, 2023). "Using an intracranial injection model for RET fusion-positive NSCLC brain metastasis in immunodeficient mice, it was reported that either Ponatinib (anti-BCR-ABL) or Selpercatinib treatment via intracranial administration significantly reduced tumor size." (PMID 36918928, 2023). "Future in vitro and in vivo studies are warranted to determine whether mentioned drugs (such as DRD2 antagonists, MAPK12 inhibitors, RET inhibitors, or drugs targeting PTN) can inhibit tumor growth and improve survival and quality of life in dogs with PPGL." (PMID 37691636, 2023). "These tumours also had similar detection rates for EGFR mutations and for RET, ROS1, ALK and MET oncogenic isoforms compared with tumours in never-smokers, which suggests that they have a similar aetiology and pathogenesis." (PMID 37046096, 2023). "Responses appeared to be durable regardless of tumor type, RET fusion type, previous treatment or presence of brain metastases." (PMID 38201460, 2023). "In MTC, RET constitutive activation accelerates EMT, which increases aggressiveness of the tumor." (PMID 37046823, 2023). "In addition, Pralsetinib exhibits in vivo functionality, both preventing and reversing tumor growth in models of PTC and RET fusion-driven NSCLC." (PMID 36918928, 2023). "In contrast, large tumor size, more aggressive types like the tall-cell type, angioinvasion, perineural invasion or extrathyroidal extension were independent predictive factors of NCOA4::RET." (PMID 37188126, 2023). "However, in a retrospective study of immunosuppressive treatment of RET fusion-positive NSCLC patients, the tumor response rate of 16 patients was only 0%." (PMID 37603207, 2023). "One of these is regorafenib, an oral multikinase inhibitor (MKI) that blocks the activity of multiple protein kinases involved in oncogenes (KIT, RET, RAF, and BEAF), tumor angiogenesis (VEGFR1, VEGFR2, VEGFR3, and TIE2), and the tumor microenvironment (PDGFR and FGFR)." (PMID 37142953, 2023). "PD-L1 tumor cell expression in the NSCLC RET fusion-positive cohort was significantly higher than in the NSCLC RET fusion-negative cohort (P < 0.001)." (PMID 36690680, 2023). "Although recurrent, pathogenic variants were observed in potential tumor-agnostic targets (NTRK, RET), none of the observed variants were rearrangements/fusions for which the current FDA approvals exist." (PMID 37888109, 2023). "Vandetanib plays an anti-tumor role by inhibiting VEGF/MAPK and RET/RHO/JNK signaling pathways." (PMID 36544713, 2022). "Regorafenib is an oral tyrosine kinase inhibitor that blocks multiple protein kinase activities, including proteins involved in the regulation of oncogenesis (KIT, RET, RAF-1 and BRAF), tumour microenvironment (PDGFR and FGFR) and tumour angiogenesis (VEGFR1, 2 and 3 and TIE-2)." (PMID 35326702, 2022).
tumor (continued). "To further elicit better predictors amongst the range of PD-L1 expression in tumor tissues, we grouped the samples based on three genetic backgrounds: sporadic cases, pseudohypoxia cluster (SDHB, VHL, EGLN1, EPAS1) and kinase signaling cluster (RET, NF1)." (PMID 36439433, 2022). "However, the combination of GPR78 and RET interferes with the interaction between RET and ATF4, down-regulating ATF4 and inhibiting the anti-tumor effect of BTZ, thus leading to chemotherapy resistance." (PMID 36551309, 2022). "Our study supports the clinical attractiveness of using SPP86 in the treatment of patients with RET-positive MTC, considering the relevant anti-tumor activity of this molecule modulated by stimulation of apoptosis/necrosis and inhibition of migration and tumor-induced angiogenesis." (PMID 36139603, 2022). "Recently, it has been reported that, differently from ALK and RET, high wild-type ROS1 endogenous expression in normal tissue may obscure ROS1 3′/5′ EI detection in the tumor counterpart." (PMID 36612287, 2022). "RET fusion could activate the downstream PI3K/AKT, RAS/MAPK, and JAK/STAT pathways, which further promoted tumor proliferation, differentiation, migration." (PMID 35707347, 2022). "Because of limited available tumor tissue from the index patient, however, we were unable to perform studies to determine whether FGFR pathway activation was responsible for RET inhibitor resistance." (PMID 35510953, 2022). "Based on the anti-tumor efficacy and safety, Selpercatinib was approved by FDA for RET fusion NSCLC on May 8, 2020." (PMID 35707347, 2022). "Lenvatinib inhibits VEGF receptors 1–3, platelet-derived growth factor receptor-α, fibroblast growth factor receptors (FGFR) 1–4, KIT, and RET, among which inhibition of VEGF receptor 2 contributes to the major pharmacological effect, including the inhibition of tumor neoangiogenesis." (PMID 35089453, 2022). "Patients with RET-fusion positive NSCLC show a high response to pemetrexed-based chemotherapy regimens, possibly due to a lower expression of thymidylate synthetase in the tumor tissue." (PMID 33671873, 2021). "This study was designed to determine whether increased MET and RET expression and activity in SCNPC could be blocked by cabozantinib to inhibit tumor growth." (PMID 33471819, 2021). "Moreover, the RET proto-oncogene is also expressed in CRPC and preclinical studies targeting RET kinase activity in SCNPC have demonstrated reduced tumor growth." (PMID 33471819, 2021). "RET gene fusions are oncogenic drivers in multiple tumor types and are known to occur in 1–2% of non-squamous NSCLC patients." (PMID 33771190, 2021). "Sorafenib is the first oral multi‐kinase inhibitor that targets VEGFR‐1, VEGFR‐2 and VEGFR‐3 to inhibit angiogenesis, the RET gene also known as RET/PTC rearrangement, RAF (including BRAFV600E) and platelet‐derived growth factor receptors to inhibit tumour progression." (PMID 34309110, 2021). "Considering the tumor suppressor functions of RET in CRC and since in CIMP, RET expression is correlated to clinicopathologic features, in this study, we aim to assess the RET expression in cancer and normal tissues and to evaluate the correlation of RET expression with clinicopathological features." (PMID 33906292, 2021). "The recruited macrophages assisted the polarization and migration of tumor cells through the GDNF/RET pathway without changing the direction of tumor migration." (PMID 34572820, 2021). "It was previously demonstrated that when inadequate inhibition of RET activity occurred after a TKI dose reduction due to side-effects, tumor inhibition by miR153-3p via mTOR signaling may provide a therapeutic advantage." (PMID 33924120, 2021). "Moreover, patients whose GC simultaneously expressed RET and GFRAL at a high level had significantly shorter survival time compared to those patients whose tumor tissue expressed both these markers at a low level (474 days vs. 2197 days, P = 0.0002)." (PMID 34149933, 2021).
tumor (continued). "Clonal RET/PTC rearrangement occurs in 10–20% of PTCs and is specific for this subtype tumor." (PMID 33669363, 2021). "A prognostic biomarker (HER2; BRAF V600E mu­tations; RET gene rearrangements; high-level MET amplification) is indicative of patient survival independent of the treatment received because the biomarker is an indicator of the innate tumor aggressiveness." (PMID 34660150, 2021). "Third, the tumor mutational burden and the LEN targets c-kit, RET, VEGFR 1-3 or PDGFR-α were not analyzed because we considered FGFR as the most relevant drug-specific target molecules." (PMID 34475850, 2021). "One more tumor harbored another previously undescribed RET fusion, TNIP1/RET." (PMID 34282777, 2021). "Notably, the RET-mutant effect required the presence of dexamethasone while the SDHB-mutant effect required its absence, providing a plausible explanation for the tumor location preference." (PMID 33947839, 2021). "Thus, though some general anti-tumour effect was noted, possibly mediated by inhibition of angiogenesis (VEGFR2), Pz-1 efficacy correlated with the positivity for RET and TRKA oncoproteins." (PMID 34373541, 2021). "As GDNF is highly expressed in NSCLC, we could hypothesize in RET inhibitors resistant cancer cells harboring MET amplification, a cross-talking between tumor microenvironment and TK receptors." (PMID 33806299, 2021). "Notably, MET+/RET+ LuCaP 93 and MET-/RET- LuCaP 173.1 tumor volumes were significantly decreased with cabozantinib treatment in vivo, and this activity was independent of MET or RET expression in LuCaP 173.1." (PMID 33471819, 2021). "Accordingly, patients in Groups B1 and B2 did differ neither in age nor in RET genetics while they differ in the biological behavior of the tumor whose growth was faster in Group B1." (PMID 34771717, 2021). "By RNA-seq analysis, we identify a RET rearrangement in the tumour material of a patient who does not harbour any known RAS or BRAF mutations." (PMID 32345963, 2020). "Cabozantinib treatment of mice bearing RET fusion-positive cell line xenografts and two PDXs significantly reduced tumor proliferation without adverse toxicity." (PMID 33318047, 2020). "By different genetic analysis, several authors reported the frequent occurrence of PTCs composed of both tumor cells with and without RET/PTC or BRAFV600E genetic alterations." (PMID 32046148, 2020). "In addition, nintedanib was recently shown to exert direct anti-tumor effect on tumor cells, but only those with oncogene addiction to growth factors receptors targeted by nintedanib, such as PDGFRα, FGFR2, FLT3, or RET." (PMID 32133285, 2020). "Recent studies show that the overexpression of GDNF at moderate levels in mice do not stimulate tumor formation, supporting the idea that transient RET activation by GFL proteins or small molecular weight ligands is safe." (PMID 32911810, 2020). "One of them was observed in a patient with a single PHEO due to a RET mutation and the three others in patients with no identified mutation (including the only MIBG-/FDG-tumour)." (PMID 32859070, 2020). "Genes related to cancer pathways were downregulated upon atezolizumab treatment, including angiogenic factors for tumor vascularization (TNK1, AREG and KDR), proto-oncogenes (RET and MET) and tumor cell survival/migration/invasion (CDH1, RARA, WNK2, WNT4A, WNT9A, TGFB2, EGF, and LAMA3)." (PMID 32616706, 2020). "Patient CRUK0056 was not a candidate to receive targeted therapies since her tumour was classified as stage IB and she did not harbour any mutation associated to known driver genes (e.g., EGFR, ALK, ROS1, BRAF, RET)." (PMID 31540260, 2019). "In our study, genes, such as GATA3, ERBB4, RET, NAT1, and TFF3, typically more expressed in ER positive tumor samples, were also more expressed in stromal cells from ER positive as compared with ER negative tumors (defined by immunohistochemistry of malignant cells)." (PMID 31817155, 2019).
tumor (continued). "RTKs, such as VEGF receptor, EGFR, fibroblast growth factor receptor, platelet-derived growth factor receptor, RET and KIT, are responsible for several biological signaling pathways involved in the regulation of angiogenesis, oncogenesis and the tumor microenvironment." (PMID 31856912, 2019). "To date, besides the first CCDC6 fusion with the tyrosine kinase RET identified in papillary thyroid cancer, additional CCDC6 fusions have been reported with PDGFRb, PTEN, FGFR2 ANK3, and UBE2D1 and with other genes in different tumor types." (PMID 31877762, 2019). "Additionally, it acts as a tyrosine kinase inhibitor targeting VEGFR1, VEGFR2, VEGFR3, PDGFRβ, ret proto-oncogene (RET), and fms-related tyrosine kinase 3, resulting in the inhibition of tumor proliferation." (PMID 30889843, 2019). "Increased alterations in 1q21 have been found before in EOCRC, although the criterion of tumor location was not applied, while 10q11.21-11.22 is a region where the RET gene is located." (PMID 30813366, 2019). "Lenvatinib is an oral, multitargeted TKI of VEGFR1-VEGFR3, RET, fibroblast growth factor receptors 1–4 (FGFR1-FGFR4), PDGFRα, and v-kit Hardy-Zuckerman 4 feline sarcoma viral oncogene homolog (KIT) signaling networks involved in tumor angiogenesis." (PMID 30619094, 2018). "These fusions and RET amplification can induce transformation of non-tumorigenic cells, support xenograft tumor formation, and render sensitivity to RET inhibition." (PMID 30446652, 2018). "Regorafenib is a potent oral inhibitor of multiple kinases which might be involved in tumor angiogenesis (VEGFR-1, -2, -3, Tie-2), oncogenesis (KIT, RET, RAF-1, BRAF, BRAFV600E), and tumor niche formation (PGDFR, FGFR)." (PMID 29371921, 2017). "Oncogenes ALK, ROS1, RET and MET have been characterized as indicators for tumor growth." (PMID 28716024, 2017). "The highest number of differentially methylated probes were detected in tumours with NF1-mutations (1651 probes) followed by those without known mutations (1184 probes), those with RET-mutations (432 probes) and those with VHL-mutations (339 probes)." (PMID 28327598, 2017). "Unpaired t-test showed that tissues sampled from tumours with postoperative metastasis achieved both higher RET nuclear and cytoplasmic expression than samples from tumours without postoperative metastasis." (PMID 27092013, 2016). "The results showed that tumours with versus without high RET nuclear expression presented more frequent distant metastasis (HR = 2.262, 95% CI: 1.527 to 3.352, p < 0.001)." (PMID 27092013, 2016). "The RET nuclear expression was selected as a rank variable, and the tumour metastasis status (presence or absence of distant metastasis) was selected as a dependent variable." (PMID 27092013, 2016). "Unpaired t-test showed that tissues sampled from tumours with distant metastasis presented higher RET nuclear expression than that of samples from tumours without distant metastasis." (PMID 27092013, 2016). "Recently an additional TKI, cabozantinib, an inhibitor of multiple receptor tyrosine kinases, including RET, MET and VEGFR2, has been reported to induce immunogenic modulation, altering tumor-cell phenotype and sensitizing tumor cells to immune-mediated attack." (PMID 26579226, 2015). "Only one of these agents, cabozantinib, which is an inhibitor of multiple receptor tyrosine kinases, including RET, MET, and VEGRF2 has been reported to induce immunogenic modulation, altering tumor-cell phenotype and sensitizing tumor cells to immune-mediated attack." (PMID 26579226, 2015). "The aim of this study, a retrospective evaluation of tumor samples from the NSCLC Phase III program, was to determine the prevalence of RET rearrangements and other potential RET biomarkers within this population and to investigate any association with outcome to vandetanib treatment." (PMID 25881079, 2015).